FCAMR (Fc alpha and mu receptor)
Description:
Functions as a receptor for the Fc fragment of IgA and IgM. Binds IgA and IgM with high affinity and mediates their endocytosis. May function in the immune response to microbes mediated by IgA and IgM.
Synonyms: CD351; FKSG87; FCA/MR; Fcalpha/muR
Tractability: Antibody: its Gene Ontology location is reachable by antibodies, with high confidence; UniProt places it where antibodies can reach, with medium confidence; UniProt predicts a signal peptide or a membrane-spanning region.
Gene: Protein-coding gene on chromosome 1 (206,957,965 to 206,970,625, reverse strand). Ensembl gene ENSG00000162897.
Subcellular location: Cell membrane
Pathways (Reactome):
Hemostasis: Cell surface interactions at the vascular wall
Gene Ontology:
Molecular function: transmembrane signaling receptor activity
Biological process: signal transduction
Cellular component: plasma membrane
Genetic constraint (gnomAD): Loss-of-function variants: 48 observed, 52.09 expected, observed/expected ratio (o/e) 0.92, 90% interval 0.73 to 1.17. The upper end of that interval is the gene's LOEUF score, 1.17, which puts it in group 5 of 6, group 1 being the genes least tolerant of losing a copy. Missense variants: 716 observed, 744.58 expected, observed/expected ratio (o/e) 0.96, 90% interval 0.9 to 1.02. Synonymous variants: 281 observed, 273.31 expected, observed/expected ratio (o/e) 1.03, 90% interval 0.93 to 1.13.
Homologues: Orthologues: chimpanzee FCAMR (98% identical), macaque FCAMR (79% identical), dog FCAMR (55% identical), rat Fcamr (50% identical), mouse Fcamr (49% identical), tropical clawed frog pigr (14% identical), zebrafish pigr (10% identical), zebrafish si:ch211-264f5.2 (10% identical), zebrafish pigrl3.5 (10% identical), zebrafish si:ch211-215e19.6 (10% identical), zebrafish si:ch211-215e19.3 (10% identical), zebrafish pigrl2.4 (9% identical), and 13 more. Paralogues in human: PIGR (20% identical), CD300LG (11% identical), FCMR (10% identical), CD300A (9% identical), CD300LF (8% identical), CD300E (8% identical), CD300C (8% identical), CD300H (8% identical), CD300LD (8% identical), TREML1 (8% identical), CD300LB (8% identical), TMIGD3 (7% identical), and 1 more.
Diseases named in the same sentence as FCAMR in open-access papers:
FCAMR is named in the same sentence as 10 diseases in open-access papers, as found by Europe PMC text mining. Sharing a sentence is not in itself a finding about the gene and the disease. The quoted sentences say what the papers report.
endometritis (4 papers, 2024 to 2025). An acute or chronic, usually bacterial infectious process affecting the endometrium. "Ewes with endometritis had a marked increase in the expression of the FCAMR gene." (PMID 40005882, 2025). "Gene expression levels were considerably higher in endometritis-affected buffaloes than in resistant ones for the genes A2M, TLR2, IRAK3, CCl2, FCAMR, iNOS, ADAMTS20, KCNT2, MAP3K4, MAPK14, FKBP5, and EPHA4." (PMID 38459095, 2024).
Arthritis (1 paper, 2025). Inflammation of a joint. "The rams with arthritis showed significantly greater levels of gene expression for the genes IL-1α, IL-1β, IL-6, IL-10, TNFα, NCF4, NFKB, TMED, FCAMR, iNOS and COX18 than did the healthy rams." (PMID 40005882, 2025). "Gene expression intensities were much higher in the arthritis-affected rams than in the healthy ones for the genes IL-1α, IL-1β, IL-6, IL-10, TNFα, NCF4, NFKB, TMED, FCAMR, iNOS and COX18." (PMID 40005882, 2025). "When comparing healthy rams to those with arthritis, the expression levels of the following genes were noticeably higher: IL-1α, IL-1β, IL-6, IL-10, TNFα, NCF4, NFKB, TMED, FCAMR, iNOS and COX18." (PMID 40005882, 2025). "This research described the antioxidant (SOD3, CAT, GPX, ATOX1 and COX18) and immunological (IL-1α, IL-1β, IL-6, IL-10, TNFα, NCF4, NFKB, TMED, FCAMR and iNOS) genes in rams that had arthritis and those that did not." (PMID 40005882, 2025).
atherosclerosis (1 paper, 2021). A disease characterized by the build-up of fatty material and calcium deposition in the arterial wall resulting in partial or complete occlusion of the arterial lumen. "Research has demonstrated that FCAMR (Fc fragment of IgA and IgM receptor) gene could contribute to progression of atherosclerosis, but this gene might be crucial for progression of T1D in patients with atherosclerosis." (PMID 33827531, 2021).
cognitive decline (1 paper, 2025). "FCAMR and CD72, both involved in B-cell activation and antibody responses, were negatively correlated with global cognition in RHI, underscoring chronic immune activation as a driver of RHI-related cognitive decline." (PMID 40524252, 2025).
coronary atherosclerosis (1 paper, 2017). Atherosclerosis of the coronary vasculature. "Candidate gene interaction studies have added much to our knowledge of air pollution and coronary atherosclerosis; our findings add to these studies by implicating additional inflammatory response genes (FCAMR and PIGR)." (PMID 28355232, 2017). "Given the proximity of the two genes, their similar functions, and LD structure we cannot completely disregard that potentially both PIGR and FCAMR are involved in mediating the effects of traffic-related air pollution on coronary atherosclerosis." (PMID 28355232, 2017).
IgA nephropathy (1 paper, 2017). "Both PIGR and FCAMR are implicated in IgA nephropathy, a condition where IgA immune complexes are deposited in the glomerular mesangium." (PMID 28355232, 2017).
prostate carcinoma (1 paper, 2021). A carcinoma that arises from epithelial cells of the prostate gland. "The downregulation of FCAMR might be associated with the dysregulation of immune system in the prostate cancer." (PMID 33808801, 2021).
tumor (2 papers, 2021). "For the top genes with lower expressions in the tumors, Fc alpha/mu receptor (FCAMR) was a novel gene identified with one of the lowest expression values in LNCaP tumor xenograft compared to LNCaP cells." (PMID 33808801, 2021).
FCAMR also shares sentences with these, for which no sentence is quoted: infection (1 paper); lung carcinoma (1).